TNFRSF14 (TNF receptor superfamily member 14)
Diseases named in the same sentence as TNFRSF14 in open-access papers (continued):
Sharing a sentence is not in itself a finding about the gene and the disease.
bacterial infection (4 papers, 2011 to 2025).
immune diseases (2 papers, 2019 to 2022). "The colocalization of several TNF receptor superfamily members (TNFRSF1A, TNFRSF9, and TNFRSF14) further supports the development of drugs modulating TNF pathway, one of the main therapy lines for treating immune diseases." (PMID 35591976, 2022).
benign tumors (1 paper, 2025). "To identify potential TNFRSF14/HVEM dysregulation in OvCa, we first analyzed the mRNA expression level of TNFRSF14 in specimens from patients with benign tumors (n = 7) and patients with OvCa (n = 26)." (PMID 40105652, 2025).
TNFRSF14 also shares sentences with these, for which no sentence is quoted: hepatocellular carcinoma (8 papers); Sepsis (6); colorectal cancer (5); diffuse large B-cell lymphoma (5); atopic dermatitis (4); Burkitt lymphoma (4); chronic lymphocytic leukemia (4); esophageal squamous cell carcinoma (4); Autoimmunity (3); Hepatitis (3); infectious disease (3); leukemia (3); Listeria infection (3); osteosarcoma (3); Acute hepatitis (2); acute myeloid leukemia (2); acute pneumonia (2); adenocarcinoma (2); allergic asthma (2); autoimmune uveitis (2); blood cancers (2); co-infection (2); colon carcinoma (2); gastric tumor (2); hematological malignancies (2); inflammation (2); kidney injury (2); lung squamous cell carcinoma (2); neuroblastoma (2); non-Hodgkin lymphoma (2).
A further 80 diseases each share a sentence with TNFRSF14 in 2 papers or fewer.